PLA2G4D (phospholipase A2 group IVD)
Description:
Calcium-dependent phospholipase A2 that selectively hydrolyzes glycerophospholipids in the sn-2 position. Has a preference for linoleic acid at the sn-2 position.
Synonyms: cPLA2delta
Tractability: Small molecule: a structure with a bound ligand is known. Antibody: UniProt places it where antibodies can reach, with medium confidence; the Human Protein Atlas places it where antibodies can reach.
Target class: Enzyme; Hydrolase
Gene: Protein-coding gene on chromosome 15 (42,067,009 to 42,094,562, reverse strand). Ensembl gene ENSG00000159337.
Subcellular location: Cytoplasm, cytosol; Membrane
Subcellular location (Human Protein Atlas): Cytosol; Plasma membrane
Pathways (Reactome):
Metabolism: Acyl chain remodelling of PC; Acyl chain remodelling of PE; Acyl chain remodelling of PG; Acyl chain remodelling of PI; Acyl chain remodelling of PS; Hydrolysis of LPC; Synthesis of PA
Gene Ontology:
Molecular function: phospholipase A2 activity; calcium ion binding; calcium-dependent phospholipid binding; phospholipase A1 activity; phospholipase activity
Biological process: glycerophospholipid catabolic process; phosphatidylglycerol acyl-chain remodeling; phosphatidylinositol acyl-chain remodeling; fatty acid metabolic process; glycerophospholipid metabolic process; phospholipid catabolic process
Cellular component: cytosol; membrane; cytoplasm
Genetic constraint (gnomAD): Loss-of-function variants: 81 observed, 93.64 expected, observed/expected ratio (o/e) 0.87, 90% interval 0.72 to 1.04. The upper end of that interval is the gene's LOEUF score, 1.04, which puts it in group 4 of 6, group 1 being the genes least tolerant of losing a copy. Missense variants: 1,049 observed, 1,035.8 expected, observed/expected ratio (o/e) 1.01, 90% interval 0.96 to 1.07. Synonymous variants: 438 observed, 435.1 expected, observed/expected ratio (o/e) 1.01, 90% interval 0.93 to 1.09.
Homologues: Orthologues: chimpanzee PLA2G4D (99% identical), macaque PLA2G4D (93% identical), dog PLA2G4D (83% identical), rabbit PLA2G4D (82% identical), pig PLA2G4D (82% identical), guinea pig PLA2G4D (73% identical), mouse Pla2g4d (71% identical), rat Pla2g4d (70% identical), tropical clawed frog pla2g4d (43% identical), tropical clawed frog jmjd7-pla2g4b (36% identical), zebrafish pla2g4f.2 (35% identical), zebrafish pla2g4f.1 (35% identical). Paralogues in human: PLA2G4B (48% identical), PLA2G4E (44% identical), PLA2G4F (40% identical), PLA2G4A (24% identical), PLA2G4C (16% identical).
Diseases named in the same sentence as PLA2G4D in open-access papers:
PLA2G4D is named in the same sentence as 11 diseases in open-access papers, as found by Europe PMC text mining. Sharing a sentence is not in itself a finding about the gene and the disease. The quoted sentences say what the papers report.
psoriasis (9 papers, 2016 to 2025). An autoimmune condition characterized by red, well-delineated plaques with silvery scales that are usually on the extensor surfaces and scalp. "PLA2G4D is expressed in keratinocytes and upregulated in psoriasis indicating a multifaceted role in the regulation of cell function." (PMID 39490928, 2024). "Among the overlapping PRP and psoriasis DEGs were several psoriasis hallmark genes, including proinflammatory cytokines and chemokines, skin barrier–related genes, and several PLA2 family genes (PLA2G2F, PLA2G4D, and PLA2G4E)." (PMID 34491907, 2021). "This led to our identification of 3 members of the PLA2 family, both soluble (PLA2G2F) and cytoplasmic (PLA2G4D and PLA2G4E), as a critical pathogenic pathway shared between PRP and psoriasis." (PMID 34491907, 2021). "Here, we show that PLA2G2F (sPLA2) and PLA2G4D/PLA2G4E (cPLA2s) are highly expressed in the epidermis of both PRP and psoriasis." (PMID 34491907, 2021). "The major common pathway shared between psoriasis and PRP involves the phospholipases PLA2G2F, PLA2G4D, and PLA2G4E, which were found to be primarily expressed in the epidermis." (PMID 34491907, 2021). "PLA2G4D, TGM1, and IL36RN are all described to be involved in the psoriasis." (PMID 27774448, 2016).
atherosclerosis (1 paper, 2017). A disease characterized by the build-up of fatty material and calcium deposition in the arterial wall resulting in partial or complete occlusion of the arterial lumen. "Of particular interest, pathway enrichment analysis of the 34 common gene associated DMRs revealed epigenetic impairment of NRF2 oxidative stress (SOD2), DNA repair (BRCA1), thioredoxin (TXNRD1) and inflammatory pathways (MIF, PLA2G4D) in atherosclerosis conditions." (PMID 28698603, 2017).
inflammatory skin disorders (1 paper, 2021). "We further confirmed expression of PLA2G2F and PLA2G4D in other hyperproliferative and inflammatory skin disorders, including squamous cell carcinoma, suggesting that expression of these PLA2s is a common pathway in diseases characterized by epithelial proliferation." (PMID 34491907, 2021).
splenic marginal zone lymphoma (1 paper, 2021). Splenic marginal zone lymphoma is a rare, indolent B-cell non-Hodgkin lymphoma characterized by abnormal clonal proliferation of mature B-lymphocytes with involvement in the spleen, bone marrow and, frequently, the blood. "PLA2G4D, a member of the phospholipase A2 enzyme family, was defined as a recurrently mutated gene that leads to the pathogenesis of splenic marginal zone lymphoma." (PMID 34193202, 2021).
PLA2G4D also shares sentences with these, for which no sentence is quoted: schizophrenia (2 papers); staphylococcus aureus infection (2); cancer (1); infection (1); liver cancer (1); melanoma (1); squamous cell carcinoma (1).